TPM3 (tropomyosin 3)
Diseases named in the same sentence as TPM3 in open-access papers (continued):
Sharing a sentence is not in itself a finding about the gene and the disease.
glioma (continued). "Colony formation and EdU assays demonstrated the inhibitory effect of sh-TPM3 and miR-29b-2-5p-mimics on the proliferation of glioma cell lines, which could be reversed after treatment with the TPM3 expression plasmid." (PMID 37305396, 2021). "TPM3 was down-regulated when sh-TPM3 or miR-29b-2-5p mimics were transfected with glioma cell lines detected by qRT-PCR, which could be restored by a TPM3 overexpression plasmid." (PMID 37305396, 2021). "Consequently, we explored the gene functions associated with TPM3 and TPM4 in glioma." (PMID 35892971, 2022). "Furthermore, bioinformatic analyses indicated that TPM3/4 could be promoting factors for poorer survival in glioma, but only TPM3 could serve as an independent prognostic factor." (PMID 35892971, 2022). "Interestingly, the univariate Cox regression analyses indicated that a high expression of TPM2/3/4 was a promoting factor for poorer survival of glioma, while the multivariate Cox regression analyses indicated that a high expression of TPM3 was an independent prognosis factor for poor prognosis." (PMID 35892971, 2022). "In this study, it was found that TPM1, TPM3, and TPM4 were significantly upregulated in gliomas, while a high expression level of TPM2, TPM3, and TPM4 was significantly correlated with poorer prognosis." (PMID 35892971, 2022). "The results showed that TPM1, TPM3, and TPM4 were significantly more highly expressed in glioma in comparison to normal tissues, while TPM2 mRNA expression showed no statistical differences." (PMID 35892971, 2022). "The results above indicated that TPM3 and TPM4 could serve as disadvantageous factors for the survival of glioma, while TPM3 served as an independent predictor of a bad prognosis." (PMID 35892971, 2022). "Since previous bioinformatic analyses indicated that TPM3 is the most representative oncogene for the TPM family in glioma, TPM3 was overexpressed or knocked down in U87-MG cells and U251 cells to further investigate the biological functions in glioma." (PMID 35892971, 2022). "Previous studies on the TPM3 gene have shown it to be involved in tumorigenesis, migration, and invasion in hematopoietic tumors as well as expression of MMP family members and EMT-like activators in gliomas." (PMID 31384394, 2019). "The results showed that TPM2, TPM3, and TPM4 were more expressed in high-grade gliomas than in low-grade gliomas, while for TPM1, the trend was not as evident as in other groups." (PMID 35892971, 2022).
papillary thyroid carcinoma (8 papers, 2000 to 2024). "Tropomyosin 3 (TPM3) contributes cancerogenesis in thyroid papillary carcinoma and esophageal squamous cell carcinoma by fusing neurotrophic receptor tyrosine kinase 1 and PDGF receptors." (PMID 32707975, 2020). "TPM3 also leaded to papillary thyroid carcinoma via rearrangement with NTRK1." (PMID 36639822, 2023). "Among pediatrics there was one case each of fibrosarcoma (TPM3::NTRK1), Ewing’s sarcoma (LPPR1::NTRK2), primitive neuroectodermal tumor (DAB2IP::NTRK2), and papillary thyroid carcinoma (RAD51B::NTRK3)." (PMID 38967220, 2024). "ALK rearrangements leading to TPM3-ALK fusion have also been reported in anaplastic large cell lymphoma and papillary thyroid carcinoma, and result in a constitutive tyrosinase kinase activity, in this way causing tumor development." (PMID 25593912, 2014). "In up to 12% of papillary thyroid cancer patients, the 3′ exons of NTRK1 with the kinase domain had been found to fuse with the 5′ exons of various thyroid-expressed genes (TPM3, TPR, TFG) in frame." (PMID 24647444, 2014). "In the ‘spontaneous’ tumours, only one of the 14 papillary carcinomas and one of the four in vitro culture cell lines, derived from a papillary carcinoma, presented a NTRK1 rearrangement also with the TPM3 gene." (PMID 10646882, 2000). "Our results concerning the radiation-associated tumours showed that only rearrangements between NTRK1 and TPM3 genes (TRK oncogene) were detected in 2/14 papillary carcinomas and in one lymph-node metastasis of one of these papillary thyroid carcinomas." (PMID 10646882, 2000). "TPM3 was specifically amplified in endometrioid tumors and the gene has been shown to constitute a fusion gene with NTRK1 which belongs to the group of TRK oncogenes reported for papillary thyroid carcinoma." (PMID 23078675, 2012).
dilated cardiomyopathy (7 papers, 2022 to 2025). Cardiomyopathy which is characterized by dilation and contractile dysfunction of the left and right ventricles. "Lamc3, for instance, was involved in the PI3K-Akt signaling pathway, while Tpm3 and Itga10 were associated with dilated cardiomyopathy." (PMID 40606020, 2025). "Next, the Tpm3 and Atp2a2 were core genes in pathway “cardiac muscle contraction”, “dilated cardiomyopathy” and “hypertrophic cardiomyopathy”." (PMID 36817606, 2023). "By combining volcano plot and GO analysis, we identified differentially expressed genes enriched in hypertrophic and dilated cardiomyopathy, including TTN, TPM3, CTTN, LAMA4, and ITGB1." (PMID 41214391, 2025). "Dilated cardiomyopathy (DCM) pathway, including Lama2, Tnnt2, Actg1, Atp2a2, Gnas, Tpm3, Itga6, Tpm1, and Pln, was enriched in the KEGG pathway." (PMID 37858115, 2023). "The results showed that genes (DES, MYH6, MYL2, MYL3, TPM1, TPM3, TPM4, and TTN) in MCODE 2 were significantly involved in dilated cardiomyopathy and hypertrophic cardiomyopathy (HCM)." (PMID 35645614, 2022).
cap myopathy (6 papers, 2020 to 2023). Cap myopathy is a very rare congenital myopathy presenting a weakness of facial and respiratory muscles associated with craniofacial and thoracic deformities, as well as weakness of limb proximal and distal muscles. "Previously, a TPM3 mutation changing nucleotide 452 from A to C resulting in amino acid 151 changing from glutamic acid (E) to alanine (A) was reported in a CM patient with cap myopathy." (PMID 33435938, 2021). "Cap myopathy represents the third diagnosis made in TPM3 patients (13%), characterized by the presence of well-demarcated structures with reduced ATPase activity in subsarcolemmal regions, referred to as cap-like structures." (PMID 37936227, 2023). "In one of the first reports describing three affected siblings with TPM3-related cap myopathy, the clinical presentation was variable and the time lapse between initial symptoms and diagnosis was very long, implying that the clinical course was rather mild." (PMID 32456280, 2020).
esophageal squamous cell carcinoma (6 papers, 2020 to 2025). Esophageal squamous cell carcinoma (ESCC) is a type of esophageal carcinoma (EC) that can affect any part of the esophagus, but is usually located in the upper or middle third. "Similarly, our previous study showed that TPM3 was upregulated in esophageal squamous cell carcinoma tissues and was associated with migration and invasiveness of ESCC cells." (PMID 35287546, 2022). "Therefore, we further explored the molecular mechanisms underlying the upregulation of TPM3 in esophageal squamous cell carcinoma." (PMID 35287546, 2022). "PCBP1 is responsible for the significant upregulation of TPM3 in esophageal squamous cell carcinoma." (PMID 37686101, 2023). "In the current study, we found that PCBP1 was responsible for the significant upregulation of TPM3 in esophageal squamous cell carcinoma." (PMID 35287546, 2022). "Taken together, PCBP1 acting as a pro-oncogenic factor enhances TPM3 mRNA stability by directly binding to the 3’UTR of TPM3 mRNA in esophageal squamous cell carcinoma." (PMID 35287546, 2022). "Although TPM3 plays a complex role in a variety of human tumors, to our knowledge, this is the first study to confirm post-transcriptional regulation of TPM3 mRNA mediated by RNA-binding proteins in esophageal squamous cell carcinoma." (PMID 35287546, 2022). "The aim of the current research is to clarify the molecular mechanisms of PCBP1 in upregulating TPM3 expression, providing a potential therapeutic target for the treatment of esophageal squamous cell carcinoma." (PMID 35287546, 2022). "TPM3 was highly expressed in esophageal squamous cell carcinoma from TCGA dataset." (PMID 35287546, 2022). "However, the reason for the upregulation of TPM3 expression in esophageal squamous cell carcinoma tissues is unclear." (PMID 35287546, 2022).
thyroid cancer (6 papers, 2014 to 2025). "Most TPM3::NTRK1 gene fusions (n = 12) were found in thyroid cancer (n = 5, 41.7%), then STS (n = 3, 25.0%)." (PMID 38925616, 2024). "Preliminary clinical activity of DS-6051b was observed in TKI-naive and crizotinib-pretreated ROS1+ NSCLC patients and a patient with TPM3-NTRK fusion-positive thyroid cancer who achieved a confirmed partial response of 27 months at the last follow-up." (PMID 35372074, 2022). "NTRK1 (neurotrophic receptor tyrosine kinase 1) also fuses to TPM3; seen in more than 5% of thyroid cancers, the event again connects the TPM3 5′ end with the NTRK1 kinase domain." (PMID 30836651, 2019). "In thyroid cancer, TPM3::NTRK1 (n = 5) was the most frequently detected fusion gene." (PMID 38925616, 2024).
endometriosis (5 papers, 2015 to 2025). The growth of functional endometrial tissue in anatomic sites outside the uterine body. "Antibodies against TPM3 are used for the early diagnosis of endometriosis." (PMID 36712973, 2022). "Serological tests using anti-TPM3 and anti-TMOD3 antibodies demonstrated higher sensitivity, specificity, and accuracy in diagnosing early stages of endometriosis (stages I and II) compared to the commonly used marker CA125." (PMID 40072086, 2025). "Elevated levels of IgM to TPM3 and IgG to TMOD3 were observed in patients with ovarian cysts, while only IgM to TPM3 was elevated in deep infiltrative endometriosis patients." (PMID 40072086, 2025). "Autoantibodies against different epitopes of tropomyosin 3 (TPM3), stomatin-like protein 2 (SLP2), and tropomodulin 3 (TMOD3) were significantly elevated in the serum of endometriosis patients with both minimal/mild and moderate/severe disease." (PMID 26240814, 2015).
hepatocellular carcinoma (5 papers, 2012 to 2023). A malignant tumor that arises from hepatocytes. "Amplification and overexpression of TPM3 are observed in hepatocellular carcinomas." (PMID 37370118, 2023). "Among these genes are TPM3, which is frequently overexpressed in human hepatocellular carcinoma, and the histone demethylase KDM6B, both of which may be involved in the epithelial–mesenchymal transition in hepatocarcinogenesis." (PMID 35557512, 2022). "Furthermore, Tropomyosin 3 has been discovered as a novel progranulin-interacting protein in hepatocellular carcinoma cells, but the biological significance of this interaction remains to be elucidated." (PMID 27220888, 2016). "In hepatocellular carcinoma (HCC) cell lines, amplification of TPM3 leads to upregulation of Snail-mediated EMT and downregulation of E-cadherin which is ultimately responsible for the migration and invasion of HCC and worse prognosis." (PMID 30836651, 2019).
hypertrophic cardiomyopathy (5 papers, 2016 to 2025). A condition in which the myocardium is hypertrophied without an obvious cause. "Changes in AS of ATP5C1, DCLK2, and MAP3K4 rewire interactions with a “Hypertrophic cardiomyopathy” pathway, and of CACNA1C, TPM3, and ITGB1 rewire interactions with the “Diabetic cardiomyopathy” pathway." (PMID 40337913, 2025).
liver cancer (5 papers, 2012 to 2024). An epithelial or non-epithelial malignant neoplasm that arises from the liver. "The high expression of TPM3 is associated with poor survival outcomes in patients with liver cancer." (PMID 37686101, 2023). "We have further shown that tropomyosin 3 was the intracellular binding partner of GEP in liver cancer cells." (PMID 25349534, 2014). "Protein expression of GEP and TPM3 was observed only in the cytoplasmof liver cancer cells by immunohistochemical staining." (PMID 22792281, 2012). "Some scholars found that TPM1, TPM2, TPM3, and TPM4 genes are expressed in liver cancer tissues with an up-regulated expression level." (PMID 37686101, 2023). "Elevated TPM3 levelswere observed in liver cancer compared with the adjacent non-tumorous liver,and patients with elevated TPM3 levels were shown to have poor recurrence-freesurvival." (PMID 22792281, 2012).
inflammatory myofibroblastic tumor (4 papers, 2019 to 2025). A multinodular intermediate fibroblastic neoplasm that arises from soft tissue or viscera, in children and young adults. "TPM3-ALK and TPM4-ALK, a fusion protein consisting of the N-terminal of TPM and the C-terminal kinase domain of ALK, have been reported in patients with inflammatory myofibroblastic tumors, with TPM3-ALK being the most commonly observed." (PMID 37686101, 2023). "In solid tumors, ALK rearrangements including TPM4-ALK and TPM3-ALK have been identified in up to 50-75% of inflammatory myofibroblastic tumors (IMT)." (PMID 35233056, 2022). "Similarly, ALK/ROS1 inhibitors (crizotinib, ceritinib) demonstrate efficacy in inflammatory myofibroblastic tumors (IMTs), NSCLC, and renal cell carcinomas (RCCs) harboring TPM3‐ALK/ROS1 fusions." (PMID 41275415, 2025). "TPM3-ALK and TPM4-ALK, which are fusion proteins consisting of the N-terminus of TPM and the C-terminal kinase domain of ALK, have been reported in patients with inflammatory myofibroblastic tumors, with TPM3-ALK being the most frequently observed." (PMID 31278140, 2019).
sarcoma (4 papers, 2014 to 2026). A usually aggressive malignant neoplasm of the soft tissue or bone. "The identification of fusion genes such as SYT-SSX1/SSX2, PAX3-FOXO1, TPM3/TPM4-ALK and EWS-FLI1 in human sarcomas has provided important insight into the diagnosis and targeted therapy of sarcomas." (PMID 25300797, 2014). "The identification of fusion genes such as SYT-SSX1/SSX2, PAX3-FOXO1, TPM3/TPM4-ALK, BCOR-CCNB3 and EWS-FLI1 in human sarcomas has provided important insight into the diagnosis and targeted therapy of sarcomas." (PMID 25300797, 2014). "NTRK fusions have been found to be more common in the spindle cell subtype of sarcomas than other subtypes with many fusion pairings having been recorded in the literature, but an NTRK-rearranged spindle cell sarcoma with a TPM3-NTRK is incredibly rare." (PMID 40151290, 2025).
cardiomyopathy (3 papers, 2017 to 2024). A disease of the heart muscle or myocardium proper. "Proteins linked to cardiomyopathy include Myosin-7 (MYH7) and Tropomyosin 3 (TPM3)." (PMID 38787940, 2024). "Downregulated lncRNA MIR133A1HG could competitively bind with hsa-miR-659-3p and hsa-miR-218-1-3p to regulate the expression of TPM3 and might influence the cardiomyopathy." (PMID 35645614, 2022).
esophageal cancer (3 papers, 2021 to 2022). A primary or metastatic malignant neoplasm involving the esophagus. "Previous studies have indicated that upregulation of TPM3 enhanced the metastatic ability of esophageal cancer cells." (PMID 35287546, 2022). "TPM3 regulates the production of MMP2/9, which boosts the proliferation, migration, and metastatic potential of esophageal cancer cells as well as the epithelial-mesenchymal transition (EMT)." (PMID 37305396, 2021).
lung adenocarcinoma (3 papers, 2019). A carcinoma that arises from the lung and is characterized by the presence of malignant glandular epithelial cells. "They reported that SRGN, TPM3, THBS1, HUWE1, and CCDC18 were enriched in lung adenocarcinoma extracellular vesicles." (PMID 30646616, 2019).
schizophrenia (3 papers, 2009 to 2014). A major psychotic disorder characterized by abnormalities in the perception or expression of reality. "SIN3A and TPM3 have also been reported to be associated with schizophrenia." (PMID 25522158, 2014). "Decreased expression of the high-molecular-weight tropomyosin isoform Tm3 (αTMslow, = tropomyosin 3/TPM3) in schizophrenia may result in an initial inhibition of neurite outgrowth followed by a significant decrease in the number and length of dendrites." (PMID 22441714, 2012).
bladder cancer (2 papers, 2022 to 2025). "The existing literature provides evidence that TPM1, TPM2, and TPM3 mRNA expression is altered in bladder cancer tissues and may be correlated with adverse clinical outcomes." (PMID 40937226, 2025). "In addition, ROC curve indicated that TPM1, TPM2, and TPM3 had significant accuracy in the diagnosis of bladder cancer." (PMID 35734544, 2022). "Therefore, TPM1, TPM2, and TPM3 are expected to be new markers for the diagnosis of bladder cancer and will play a potentially great value in clinical conversion application." (PMID 35734544, 2022). "The expression levels of TPM1, TPM2, TPM3, and TPM4 in low grade bladder cancer were lower than those in high grade bladder cancer (P < 0.05)." (PMID 35734544, 2022). "The expression levels of TPM1, TPM2, TPM3, and TPM4 in low-grade bladder cancer were lower than those in high-grade bladder cancer." (PMID 35734544, 2022).
cardiac hypertrophy (2 papers, 2024 to 2025). "Conversely, silencing endogenous circITGa9 or inhibiting its binding to TPM3 effectively released TPM3 from its detrimental effects, thereby mitigating cardiac hypertrophy and fibrosis." (PMID 38323094, 2024). "Our study yielded significant insights into the role of circITGa9 in cardiac hypertrophy and fibrosis, primarily through its interaction with TPM3 and subsequent activation of actin polymerization." (PMID 38323094, 2024). "Developing safe and effective technologies that target cardiac hypertrophy and fibrosis, specifically focusing on circITGa9 and its interaction with TPM3, would be a crucial area of future research and development." (PMID 38323094, 2024). "We demonstrated that circITGa9, by binding to TPM3, promotes cardiac hypertrophy and fibrosis." (PMID 38323094, 2024).
fibrosarcoma (2 papers, 2020 to 2024). A malignant mesenchymal fibroblastic neoplasm affecting the soft tissue and bone. "The NTRK gene and fusion partner was TPM3::NTRK1 (fibrosarcoma), LPPR1::NTRK2 (Ewing’s sarcoma), DAB2IP::NTRK2 (primitive neuroectodermal tumor), and RAD51B::NTRK3 (PTC)." (PMID 38967220, 2024). "Of the NTRK fusion partners we identified in pediatrics, TPM3::NTRK1 (fibrosarcoma) has been documented in pediatrics by others, and DAB2IP::NTRK2 (primitive neuroectodermal tumor) has been previously documented in adults." (PMID 38967220, 2024).
gastric tumor (2 papers, 2019 to 2023). "In addition, the gastric tumor with TPM3::NTRK1 (T8;N10) rearrangement also simultaneously carried the p.G12C mutation in the KRAS oncogene." (PMID 37686416, 2023).
muscular dystrophies (2 papers, 2012 to 2018). "Many patients with significant respiratory impairment remained ambulant, a feature also shared with early onset SEPN1‐, NEB‐, TPM3‐ ACTA1‐myopathy and COL6‐muscular dystrophy." (PMID 29691892, 2018).
Myocardial fibrosis (2 papers, 2024 to 2025). "Based on these results, we have proposed a model to hypothesize how circITGa9, TPM3, and actin play roles in myocardial fibrosis." (PMID 38323094, 2024).
neuroblastoma (2 papers, 2010 to 2018). Neuroblastoma (NB) is the most common solid, extracranial childhood tumor. "Notably, we compared the presence of the specific cassette exons in RNA from normal brain and neuroblastoma (for ATP6v0A1, STRADA, PCNP and CS) and from skeletal muscle and rhabdomyosarcoma (for TPM3, TPD52L2, NAP1L1, METT10 D and SLC25A3)." (PMID 20813049, 2010).
non-small cell lung carcinoma (2 papers, 2018 to 2022). A group of at least three distinct histological types of lung cancer, including non-small cell squamous cell carcinoma, adenocarcinoma, and large cell carcinoma. "Therefore, ALK fusion proteins are already important clinical targets in non-small cell lung cancer (EMLA4-ALK) but have also been described in diffuse large cell lymphoma (NPM-ALK) and in inflammatory myofibroblastic tumour (TPM3-ALK)." (PMID 30290811, 2018).